CXCL10 (C-X-C motif chemokine ligand 10)
Diseases named in the same sentence as CXCL10 in open-access papers (continued):
Sharing a sentence is not in itself a finding about the gene and the disease.
asthma (100 papers, 2007 to 2025). "Human airway epithelial cells produce IFN-γ inducible protein-10 (IP-10)/C-X-C motif chemokine (CXCL) 10 in vitro and in vivo upon rhinovirus infection, The release of IP-10 is closely associated with acute virus-induced asthma." (PMID 40636260, 2025). "A previous study performed children asthma patients showed the associations between higher serum CXCL10 levels and disease exacerbation and severity." (PMID 37029363, 2023). "Genotyping an asthma-susceptible IRAK-M SNP rs1624395 and measurement of serum CXCL10 levels were performed in asthma patients." (PMID 37029363, 2023). "CXCL10 was proven to be a useful inflammatory marker of occupational asthma exacerbation caused by wood dust." (PMID 35743888, 2022). "A CXCR3-dependent amplificatory mechanism also aligns with the association of airway CXCL10 expression with an IFN-γ–high asthma phenotype in human subjects and mice." (PMID 31445933, 2020). "For example, a 10-fold increase in RV RNA was associated with a 11-fold increase (95% CI 1.9, 70) in CXCL10 secretion in the normal group, compared to only a 1.5 fold increase (95% CI 0.49, 4.6) in the asthma group." (PMID 24219422, 2013). "A previous study of cord blood found associations between higher CXCL10 levels in infancy and asthma later in life, contradictory to our findings, but decreased levels of CXCL11 that were associated with allergic sensitization later in life, in line with our study." (PMID 38270326, 2024). "The stimulative effect of ADP on asthma allergies may be caused by the infiltration of MCs, where CXCL10 plays an important role." (PMID 34291079, 2021). "In addition, bone-marrow-derived macrophages isolated from Lyz2cre:Bmal1flox animals and stimulated with LPS ex vivo exhibited a higher expression of the asthma-relevant chemokines CCL2, CXCL10, as well as the asthma-associated mannose receptor." (PMID 31931006, 2020). "Furthermore, a tendency of negatively association between cord blood CXCL10 and mite sensitization was observed mainly after the age of 2 years, which is the age at which the prevalence of mite sensitization and asthma increases markedly." (PMID 27863395, 2017). "Our results suggest that the exposure to high levels of CXCL10 (IP-10) during gestation may predispose the fetus to asthma-like symptoms in infancy, however the third quartile level of this cytokine was protective." (PMID 22805009, 2012). "This study aimed to investigate using transcriptomic and metabolomic analyses of blood samples, genes like CXCL10 and metabolites such as succinic acid were found to be related to asthma." (PMID 39858200, 2025). "We demonstrated that asthma patients carrying homozygote G/G had significantly higher levels of serum CXCL10 than those carrying homozygote A/A (41.4 ± 7.8 pg/ml vs 38.1 ± 3.3 pg/ml, p = 0.03)." (PMID 37029363, 2023). "CXCL10 was upregulated in asthma and LCP1, CCR1, PRKCB, IRAK2, LILRA1, and ZEB1 were significantly upregulated in COPD patients." (PMID 36829591, 2023). "Activated airway epithelial cells are the major source of CXCL10 in the lungs, which has been shown to be involved in both bronchial inflammation and airway hyper-responsiveness in a mouse model of asthma." (PMID 37029363, 2023). "Asthma patients carrying G/G genotypes had significantly higher levels of serum CXCL10 than those carrying homozygote A/A." (PMID 37029363, 2023). "Asthma patients carrying homozygote G/G of rs1624395 had a significantly higher level of serum CXCL10 than those carrying homozygote A/A." (PMID 37029363, 2023). "Serum CXCL9 levels in asthma patients are positively correlated with CXCL10 and CXCL11 levels, which are also CXCR3 ligands." (PMID 37005469, 2023). "High levels of CXCL10 have been correlated with asthma severity, including airflow limitation, as well as predictive of viral‐induced asthma exacerbations, which is in line with our results." (PMID 38006384, 2023).
asthma (continued). "CXCL10 can promote airway inflammation and hyperresponsiveness, and virus-induced exacerbation of asthma, resulting in poor response to glucocorticoids." (PMID 35187081, 2022). "Both in a mouse model of severe asthma and in humans with severe asthma, CXCL-10 was shown to play a critical role in corticosteroid resistance and Th1-mediated inflammation." (PMID 33597172, 2021). "Since safranal showed effect on reducing mast cell infiltration in OVA-induced asthma model and RNA sequencing reveals regulation of Cxcl10 and Ccl7, we proceed with the in vitro experiment." (PMID 34093515, 2021). "As result suggested that safranal regulated Cxcl10 gene, this gene is related to occurrence of asthma, we found that safranal decrease the level of Cxcl10 in lung tissue of OVA-treated mice (Supplementary 3)." (PMID 34093515, 2021). "CXCL9 and CXCL10, which have been shown to be induced in other mouse models of asthma and A. fumigatus-induced inflammation (34, –, 36), activate Th1-type immune responses through CXCR3." (PMID 33597172, 2021). "Cultures from asthma donors had higher CXCL10 and CCL5 gene expression (along with a further 44 genes) after RV infection, compared to healthy donors." (PMID 32499788, 2020). "These chemokines especially serum CXCL10 are increased in asthma and COPD exacerbations triggered by rhinoviral infections." (PMID 31395050, 2019). "CXCL10 induces chemotaxis, apoptosis, cell growth inhibition and angiostasis, and CXCL10 concentrations are significantly up-regulated in patients with asthma, COPD, pulmonary tuberculosis, and other airway inflammatory diseases." (PMID 31737787, 2019). "Increased CXCL10 levels are associated with many inflammatory pulmonary conditions including asthma thus CXCL10 expression, and receptors, are potential targets for novel therapies including inhaled IFN-γ." (PMID 30943978, 2019). "The expressions of cysteinyl leukotrienes (cysLTs) and CXCL10 are upregulated in virus-induced asthma." (PMID 30323811, 2018). "Specifically, concentrations of serum CXCL10 are elevated in virus or RV-induced asthma; correlations are reported between higher levels of CXCL10 and disease severity, including airflow limitation." (PMID 30323811, 2018). "The sputum inflammatory mediator profiles were distinct with increased TH2 (IL-5, IL-13, and CCL26) and TH1 mediators (CXCL10 and 11) in severe asthma compared with COPD and increased IL-6, CCL2, CCL3, and CCL4 in COPD compared with severe asthma." (PMID 25129678, 2015). "In this context, it would be of interest if the posttranscriptional regulation of CXCL10 in asthma occurs through the recently described modified translation control." (PMID 23606796, 2013). "In this case, a 10-fold increase in RV RNA was associated with a 56-fold increase (95% CI 14, 230) in CXCL10 mRNA in the normal group, compared to a 2.8-fold increase (95% CI 1.2, 6.8) in CXCL10 mRNA in the asthma group." (PMID 24219422, 2013). "Overall, RV replication was positively related to CXCL10 secretion and induction of IFNB1 and IL28 mRNA, but the positive relationship between RV RNA and CXCL10 secretion was stronger in normal subjects than in subjects with asthma." (PMID 24219422, 2013). "In cells from normal individuals, RV infection induced secretion of CXCL10 and TNFα; these responses were significantly blunted in the asthma group." (PMID 24219422, 2013). "The observed insensitivity of IFNγ- or cytomix-induced CXCL10 to current asthma medications emphasizes the need for novel compounds that can inhibit these nonresponsive pathways." (PMID 23034049, 2012). "An interaction of CXCL10/CXCR3 has been reported to contribute to the migration of mast cells into airway smooth muscle in asthma." (PMID 21939519, 2011).
asthma (continued). "During the occurrence of asthma, the abnormal expression of inflammation-related genes such as CXCL10 and CCL8 is closely intertwined with the disorders of mitochondrial oxidative phosphorylation and the tricarboxylic acid cycle, constituting a complex regulatory network." (PMID 39858200, 2025). "However, there is also prior evidence that up to one-third to half of patients with severe asthma may have a type 1 inflammatory signature in their airways which is associated with more severe disease and corticosteroid resistance and potentially involving the interferon-gamma/CXCL10 axis." (PMID 38710930, 2024). "Thus, a positive correlation of asthma with systemic IL-10 and organoid expression of Tnf, Cxcl10, Cldn5, Cldn4 in the A group was found." (PMID 38255939, 2024). "Whether RSV infection, COPD, and asthma function via the miR-34b/c-5p/CXCL10 axis needs to be further investigated by collecting more clinical samples." (PMID 36829591, 2023). "Moreover, we found IRAK-M SNPs rs1624395 and rs1370128 both influenced the serum concentrations of CXCL10 in patients with adult asthma." (PMID 37029363, 2023). "In addition, we only measured the serum concentration of CXCL10 in asthma patients, the most studied and important for asthma pathogenesis among three CXCR3 chemokines." (PMID 37029363, 2023). "Hence, extracellular ADP can activate the NF-κB signaling pathway, inducing nuclear translocation and phosphorylation of p65 to promote the expression of CXCL10, whereby participating in the asthma-induced lung inflammation." (PMID 34291079, 2021). "Subsequently, the experimental results of the current study uncovered that the NF-κB signaling pathway was activated by extracellular ADP through the P2Y1 receptor, by which expression of CXCL10 was promoted, and MC infiltration and airway inflammation were thereby accelerated in asthma." (PMID 34291079, 2021). "Therefore, this study was designed to explore the potential role of extracellular ADP, an agonist of P2Y1 receptor in CXCL10-mediated MC infiltration and airway inflammation in asthma." (PMID 34291079, 2021). "However IFN-regulated chemokines Cxcl9 and Cxcl10, both of which have been observed in the airways of patients with severe asthma, were reduced following miR-155-5p and miR-99a-5p inhibition." (PMID 33846533, 2021). "CXCL10 promotes airways inflammation and airways hyperresponsiveness in mouse models of asthma." (PMID 26810609, 2016). "In addition, the interaction of CXCL10 with CXCR3 has been reported to contribute to mast cells migration into airway smooth muscle in asthma." (PMID 27727269, 2016). "Additionally, CCL5 (aka RANTES), CXCL10 (aka IP-10) were also chosen for comparison experiments because these chemokines were known mediators in asthma that are differentially sensitive to vitamin D." (PMID 26207385, 2015). "Interestingly, genes previously associated with asthma, such as CCL5 (RANTES), CXCL10 (IP10), LGALS9, CX3CL1, C5AR1, and CDHR3 fall into these three different groups." (PMID 25706956, 2015). "CXCL10 may also mediate CXCR3+T lymphocyte recruitment to the ASM in severe asthma and following allergen challenge." (PMID 24648846, 2014). "ASMCs of asthma patients secrete proinflammatory chemokines CXCL10, CCL11, and RANTES which attract immune cells into the airways and may thereby initiate inflammation." (PMID 23606796, 2013). "In addition, CXCL10 secretion by ASMC is sensitive to changes in cellular glutathione (GSH) levels, suggesting a link of this signaling pathway to the asthma-associated upregulation of mitochondria, which control the cellular redox system." (PMID 23606796, 2013). "A wide range of asthma relevant stimuli have been reported to increase signaling pathways that may lead to incerased CXCL10 secretion." (PMID 23606796, 2013).
asthma (continued). "Studies of endobronchial biopsy specimens and BAL fluid of subjects with severe asthma have shown that asthma is associated with elevated bronchial mucosal expression of TSLP and Th1-attracting (IP-10/CXCL10) and Th2-attracting (TARC/CCL17, MDC/CCL22) chemokines." (PMID 22523502, 2012). "In this study evidence of how current asthma therapies affect asthmatic ASMC CXCL10 release induced when different cytokines are present and the first evidence that salmeterol may sometimes increase CXCL10 release has been provided." (PMID 23034049, 2012). "Thus the thiazolidinediones inhibited asthmatic ASMC CXCL10 release under conditions when common asthma therapies were ineffective or enhanced it." (PMID 23034049, 2012). "The effect of current asthma therapies on cytokine-induced CXCL10 release were stimulus specific." (PMID 23034049, 2012). "The findings reported here may have clinical relevance because CXCL10 production in the airway mucosa of people with asthma is increased by oral corticosteroids." (PMID 23034049, 2012). "Taken together, these findings indicate that CXCR3/CXCL10 axis may play a pivotal role in the pathogenesis of asthma through recruitment of T cells, as well as other inflammatory cells, into airways and lung parenchyma." (PMID 21939519, 2011). "Besides, we first demonstrated that salubrinal reduced LPS-driven CXCL10 expression in J774A.1 macrophage, indicating the interaction between DUSP2 and CXCL10 may be the potential mechanism for steroid-resistant asthma." (PMID 37208441, 2023). "Furthermore, mast cell numbers correlated with CXCL-10 expression in asthma." (PMID 35558068, 2022). "Furthermore, CXCL10 overexpression can induce infiltration of MCs to aggravate asthma." (PMID 34291079, 2021). "CXCL10 may also play a role in the virus-induced asthma exacerbation." (PMID 30323811, 2018). "The effects of MC from people with asthma on asthmatic ASM cell CXCL10 production may be different." (PMID 24648846, 2014). "In biopsies, there was also downregulation of the important mast cell chemoattractants CXCL10 and CXCL11 which promote mast cell migration to the ASM in mild steroid-naive asthma through the airway mast cell chemokine receptor CXCR323." (PMID 38686450, 2024). "Serum concentration of CXCL10 and genotyping of IRAK-M rs1624395, which is completely interlocked with rs1370128, were performed in 137 individual patients with asthma." (PMID 37029363, 2023). "In contrast to IFN-γ, corticosteroids suppressed LPS-induced CXCL10 gene expression, thus establishing the IFN-γ-CXCL10 axis as a critical player in corticosteroid-refractory asthma." (PMID 36032162, 2022). "We made the observation that GC insensitivity present in ASM cells derived from severe asthma was also reported to be gene-specific with CCL5, IL-6 and CCL11 being resistant to dexamethasone (or fluticasone), while CXCL10 still being repressed by either GCs." (PMID 35387008, 2021). "In conclusion, high levels of extracellular ADP in asthmatic mice can augment CXCL10-evoked MC infiltration through P2Y1 receptor, thereby aggravating the airway inflammation in asthma." (PMID 34291079, 2021). "Taken together, the extracellular ADP augmented CXCL10-mediated MC infiltration through activating P2Y1 receptor/NF-κB, thereby aggravating the airway inflammation in asthma." (PMID 34291079, 2021). "The obtained results demonstrated that extracellular ADP stimulated the CXCL10-mediated MC infiltration through the P2Y1 receptor, thereby aggravating airway inflammation in asthma." (PMID 34291079, 2021). "Studies have shown IFNγ+ CD4+ T cells are more prevalent in the airways in severe asthma versus mild, moderate disease and that IFNγ-induced expression of CXCL10 and down-regulation of SLPI lead to increased AHR and steroid resistance in severe asthma." (PMID 33101299, 2020). "In asthma, the ASM produces the chemokine CXCL10 which we have previously shown induces MC chemotaxis through CXCR3 engagement." (PMID 24648846, 2014).
asthma (continued). "Thus CXCL10 may be critical in asthma because it can induce airway myositis." (PMID 24648846, 2014). "In the following, we will focus on ASMC-derived chemokines CXCL10, CCL11 (eotaxin), and RANTES, which are crucially involved in the trafficking of immune cells into the airway in asthma." (PMID 23606796, 2013). "Interleukin-1β, CXCL10 (IP-10), and TNF are all Th1 polarized cytokines that play a role in the pathogenesis of asthma." (PMID 22583375, 2012). "Interferon-γ inducible CXCL10, one of CXCR3 ligands, is abundantly expressed in bronchiolar epithelial cells and airway smooth muscle cells of patients with asthma." (PMID 21939519, 2011). "DiABZI induced an increased release of lactate dehydrogenase (LDH), IFNα, IFNβ, IFNλ, CXCL10, IL‐6 and TNFα protein and overexpression of MUC5AC transcript in healthy epithelial cells sensitized with HDM, and less in epithelial cells from patient with asthma." (PMID 39466641, 2025). "CXCL-10, CCL-5,and TNF-R2 were the strongest discriminatorsof an asthma attack." (PMID 38339210, 2024). "Additionally, we examined the levels of inflammatory cytokines in sputum and found that IL‐5, IL‐6, IL‐8, TNF‐α, IFN‐γ, CCL17, CCL22, CXCL10, CCL4, CCL2, IL‐4, IL‐13, and CCL26 were significantly lower in stable asthma than in acute asthma." (PMID 39508721, 2024). "Ruxolitinib’s potent inhibition of CXCL10 production is an important finding because this chemokine recruits Th1 cells via the cognate receptor CXCR3 and thus contributes significantly to Th1-high asthma and failure to respond to corticosteroids." (PMID 36059986, 2022). "Recent studies have revealed that IFNγ could up-regulate and down-regulate the expression of CXCL10 and SLPI, respectively, which further resulted in increased AHR and steroid resistance in severe asthma." (PMID 35187081, 2022). "Furthermore, ADP stimulated alveolar epithelial cells to secrete chemokine CXCL10 by activating P2Y1 receptor, whereby promoting asthma airway inflammation." (PMID 34291079, 2021). "The researchers found that the expression of mRNA-encoding TSLP, TARC/CCL17, MDC/CCL22 and IP-10/CXCL10, other than I-TAC/CXCL11 and I-309/CCL1, were significantly increased in severe asthma and COPD patients compared to the non-smoking control group." (PMID 34301307, 2021). "In asthma, the airway smooth muscle (ASM) produces CXCL10 which may attract CXCR3+ mast/T cells to it." (PMID 24648846, 2014). "Further, ASM in biopsies from people with asthma are often (~50%) immunoreactive for the CXCR3 ligand CXCL10, whereas the ASM in biopsies from people without asthma are not." (PMID 24648846, 2014). "Few sputum cytokine concentrations changed in response to dexamethasone IL-17 and IFNα increased in smokers, CCL4 increased in never smokers and CCL5 and CXCL10 reduced in ex-smokers with asthma." (PMID 23951170, 2013). "This assumption was supported by studies in ASMC of asthma patients, which expressed higher levels of CXCL10 than ASMC derived from nonasthmatic controls." (PMID 23606796, 2013). "In this paper we describe how ASMC-derived CXCL10, CCL11, or RANTES may contribute to airway inflammation in asthma and how these chemokines can be controlled by the anti-inflammatory action of DMF." (PMID 23606796, 2013). "In contrast, there was a positive correlation between RV RNA level and CXCL10 secretion in cells from normal individuals (r = 0.36, p = 0.01), but not in cells from subjects with asthma (r = 0.17, p = 0.48; interaction term p=0.07)." (PMID 24219422, 2013). "RV RNA was positively correlated with CXCL10 mRNA in both groups (no asthma r = 0.61, p < 0.0001; asthma r = 0.57, p < 0.0001), but the slope was significantly greater in the no asthma group (interaction term p = 0.0008)." (PMID 24219422, 2013). "CXCL10, CCL11, and RANTES derived from ASMC are believed to be crucially involved in chemotaxis of immune cells into the asthmatic airways and are therefore actively involved in the development of airway inflammation in asthma." (PMID 23606796, 2013).